RCC1 (regulator of chromosome condensation 1)
Diseases named in the same sentence as RCC1 in open-access papers (continued):
Sharing a sentence is not in itself a finding about the gene and the disease.
tumor (42 papers, 2010 to 2025). "IHC staining of the tumor tissues showed that the RCC1 knockdown caused an increase in SIRT3 protein expression in vivo." (PMID 41391757, 2025). "Next, we analyzed the tumor mutation landscape of RCC1/SNHG3/SNHG12 expression in KICH using the SangerBox tool." (PMID 36148010, 2022). "Coherent data demonstrate the association of RCC1 with the tumor mutation burden and microsatellite instability in various tumors." (PMID 34298996, 2021). "RCC1 mutations or methylation can be key to tumor development, with this process showing the potential to inhibit tumors and regulate DNA replication." (PMID 33102517, 2020). "In clinical and basic studies, RCC1 is more commonly involved in tumor development and progression in this manner than direct RCC1 mutations or RCC1 gene silencing." (PMID 33102517, 2020). "However, in some tumors, high expression of RCC1 will also act as a pathogenic partner, promoting tumor development." (PMID 33102517, 2020). "In addition, the tumor suppression effect caused by RCC1 knockdown could be rescued by EZH2 overexpression in vitro." (PMID 37747077, 2023). "Therefore, mutations of the RCC1 gene have the potential for tumor development." (PMID 33102517, 2020). "In parallel, the impact of RCC1 depletion on tumor progression was evaluated in xenograft models using immunodeficient mice." (PMID 41281944, 2025). "Other genes such as ABCB5, CLDN5, RCC1 have also been implicated in CRC-related processes, with several studies suggesting their potential value in tumor diagnosis, progression monitoring, or prognostic evaluation." (PMID 40893943, 2025). "Multivariate Cox regression analysis further confirmed that RCC1 expression was an independent prognostic factor after adjustment for tumor grade, T stage, and N stage (P < 0.05)." (PMID 41281944, 2025). "A growing body of evidence emphasizes the critical role of RCC1 in tumor biology, primarily through its regulation of the cell cycle and influence on tumor progression." (PMID 40163507, 2025). "In tumor tissue, 65.6% of samples exhibited high RCC1 expression compared with only 20% in adjacent normal tissues [left]." (PMID 41281944, 2025). "When combined with 5-FU or Doxo, RCC1 knockdown further decreased tumor burden compared to chemotherapy alone, suggesting enhanced drug sensitivity." (PMID 41281944, 2025). "A histogram and chi-square analysis confirmed significantly elevated RCC1 expression in tumor tissues (P < 0.001)." (PMID 41281944, 2025). "Altogether, these studies implicate that RCC1 plays critical roles in cell cycle progression and proliferation of tumor cells." (PMID 38561375, 2024). "Among the MUGs, high expression of KIF11 and RCC1 was commonly correlated with high tumor grades (G2 and G3) and unfavorable clinical outcomes (treatment response-PD, SD, and post-treatment outcome-RP)." (PMID 38741142, 2024). "We also explored the relationship between RCC1 expression and clinical characteristics and found that RCC1 expression was positively correlated with nodal metastasis, tumor grade, and TNM stage in the TCGA dataset." (PMID 37747077, 2023). "The UALCAN and KM plotter portals were used to analyze the expression profile and related tumor prognosis of RCC1 in ccRCC using data from TCGA." (PMID 37747077, 2023). "Animal experiments were performed to verify the suppressive effect of RCC1 knockdown on tumor growth in vivo." (PMID 37747077, 2023). "Compared with tumors treated with sh‐NC, the tumors treated with sh‐RCC1 grew more slowly and reached a lower tumor weight and a smaller tumor volume." (PMID 37747077, 2023). "TCGA data visualized by the GEPIA and UALCAN portals showed that patients with high TNM stage and poor tumor grade had high expression levels of RCC1." (PMID 37747077, 2023). "For example, in lung cancer, RCC1 was shown to regulate the tumor sensitivity to immunotherapy by controlling PD‐L1 expression." (PMID 37747077, 2023).
tumor (continued). "In a subset of tumors, high expression of RCC1/SNHG3/SNHG12 caused enhanced mitotic and DNA damage repair processes in tumor cells, thereby enhancing cell viability and promoting cell proliferation." (PMID 36148010, 2022). "The strong tumor correlation shown by RCC1/SNHG3/SNHG12, especially RCC1, in tumor diseases deserves further investigation." (PMID 36148010, 2022). "The IHC staining indicated that of the low expression of RCC1 tumours related higher PD‐L1 expression." (PMID 33630417, 2021). "Based on the combination of TCGA and GTEx datasets, a supplementary analysis of the expression of RCC1 in tumor tissues was performed." (PMID 34298996, 2021). "RCC1 was expressed in the nucleus of glandular cells in the primary tumor, normal tissues and liver oligometastases." (PMID 34924821, 2021). "In vivo, knockdown of RCC1 significantly slowed down the growth rate of tumour, and further reduced the volume and weight of tumour model after treated by PD‐L1 monoclonal antibody." (PMID 33630417, 2021). "Our research found that RCC1 has tumor-promoting effects in most tumors including BRCA, KIRC, LGG, and LUAD, while it seems to have tumor-suppressing effects in ESCA, COAD, READ and STAD." (PMID 34298996, 2021). "RCC1 expression of different tumors in TCGA dataset was analyzed by use of the Tumor immune estimation resource version 2 (TIMER2) tool." (PMID 34298996, 2021). "The TCGA dataset was divided into a group with high expression and a group with low expression of RCC1 to explore the correlation between RCC1 expression and the prognosis of different tumor patients." (PMID 34298996, 2021). "Although the expression of RCC1 in these four kinds of digestive tract tumors is higher than that in normal tissues, the high expression of RCC1 is correlated with a better prognosis and the expression of RCC1 in COAD is negatively correlated with tumor stage." (PMID 34298996, 2021). "Using MEXPRESS tool, the potential relationship between RCC1 DNA methylation and tumor pathogenesis in TCGA cohort tumors was explored." (PMID 34298996, 2021). "Our findings therefore suggest RCC1 as a new prognostic biomarker and therapeutic target for immunotherapy in different tumor types." (PMID 34298996, 2021). "In this study, numerous genetic analysis tools, such as GEPIA2, TIMER2 and UALCAN, were applied to analyze more than 10,000 samples retrieved from TCGA, GEO, GTEx and CPTAC datasets on the expression of RCC1 gene in 33 tumor entities." (PMID 34298996, 2021). "Enrichment analysis showed that some tumor-related pathways such as “cell cycle” and “RNA transport” were involved in the functional mechanism of RCC1." (PMID 34298996, 2021). "Within 20 days, RCC1 xenografts were established with the tumor volume close to 100 mm3 (labeled “Day-0”)." (PMID 34285190, 2021). "A genomewide expression profile analysis of cervical cancer showed that the expression of RCC1 in higher staged tumor tissue (FIGO III) was higher than that of normal cervix." (PMID 34298996, 2021). "Positive RCC1 expression was observed in 81.4% (57/70) of primary tumor tissues, 18.6% (13/70) of normal tissues, and 71.3% (92/129) of liver oligometastatic tissues." (PMID 34924821, 2021). "We mainly focus on the effect of RCC1 on the cell cycle during tumorigenesis and the recent research progress that has been made in relation to different tumor types." (PMID 33102517, 2020). "RCC1 knockdown significantly reduced tumor volume and weight, indicating suppressed CRC growth." (PMID 41281944, 2025). "Collectively, these findings suggest that RCC1 knockdown may modulate the DDR signaling cascade to favor tumor suppression via apoptosis and growth arrest." (PMID 41281944, 2025). "To further investigate whether the suppressive effect of RCC1 knockdown on tumor cell proliferation was mediated by SIRT3, we performed a SIRT3 knockdown in the RCC1-knockdown PANC1 cells." (PMID 41391757, 2025).
tumor (continued). "Future studies should investigate the broader physiological impact of RCC1 inhibition, identify potential toxicities in normal tissues, and develop tumor-specific targeting strategies such as nanoparticle-based delivery or selective small-molecule inhibitors to minimize off-target effects." (PMID 40163507, 2025). "In glioblastoma, RCC1 knockdown promoted the effect of radiation on tumor stem cells." (PMID 37747077, 2023). "In the current study, we found that RCC1 was mostly overexpressed in ccRCC tissues compared with adjacent normal tissues, which indicated that RCC1 may act as a tumor promoter." (PMID 37747077, 2023). "Further functional experiments confirmed that RCC1 knockdown suppressed tumor growth and induced cell apoptosis and G1 phase arrest, while the overexpression of RCC1 had opposite effects and facilitated tumor progression." (PMID 37747077, 2023). "Then, we used RNA‐seq to evaluate the biological function of SNORA73B in EC and found that SNORA73B could not only affect the expression of a series of tumour‐related genes but also affect the alternative splicing of RCC1." (PMID 37488742, 2023). "This also suggests that RCC1 plays an important role as a potential biomarker in tumor diseases." (PMID 36148010, 2022). "At the same time, RCC1/SNHG3/SNHG12 may in turn influence the regulation of immune cell infiltration in this tumor by directly or indirectly regulating the proliferation and differentiation of some immune cells." (PMID 36148010, 2022). "RCC1 protein expression levels were evaluated in both primary tumor and its liver metastasis." (PMID 34924821, 2021). "In addition, it was also observed that the expression of RCC1 was positively correlated with the tumor infiltration level of CD8+ T-cells in THYM and UVM (all p < 0.05)." (PMID 34298996, 2021). "RCC1 expression is closely related to the prognosis of a broad variety of tumor patients." (PMID 34298996, 2021). "In addition, the S47 locus of RCC1 has a higher phosphorylation level in the primary tumor tissue of UCEC than in normal tissue (p < 0.001)." (PMID 34298996, 2021). "RCC1 regulates the cell cycle and was shown to be related to DNA damage and tumor development." (PMID 34298996, 2021). "All of these results indicate that the differential expression and function of RCC1 may depend on the type of tumor." (PMID 34924821, 2021). "RCC1 catalyses the RanGDP to RanGTP which might participate in the proliferation, invasion and metastasis of tumour." (PMID 33630417, 2021). "On the other hand, down‐regulation of RCC1 expression could inhibit tumour growth both in vitro and in vivo." (PMID 33630417, 2021). "Furthermore, the relationship between the expression of RCC1 and microsatellite instability (MSI)/tumor mutation burden (TMB) of the tumors in TCGA cohort was analyzed." (PMID 34298996, 2021). "In recent years, more and more evidence has been published on the role of RCC1 in tumor biology." (PMID 34298996, 2021). "Still, the expression and function of RCC1 depend on the different tumor types." (PMID 34298996, 2021). "Targeting RCC1 can induce tumor cell apoptosis and cell cycle arrest." (PMID 33102517, 2020). "Current research data indicate that differences in expression and function of RCC1 may depend on the type of tumor." (PMID 33102517, 2020). "All of these data indicate that differences in RCC1 expression and function may depend on the type of tumor." (PMID 29789527, 2018). "RCC1 is an important cell cycle regulator, playing a vital role in nuclear mass transport, mitosis, and nuclear membrane assembly, regulating the occurrence of S‐stage chromosome aggregation, and participating in the regulation of tumour occurrence and development." (PMID 37488742, 2023). "Moreover, in vivo animal experiments proved that targeting RCC1 could significantly restrain tumor growth, providing evidence for the potential therapeutic value of RCC1 in ccRCC." (PMID 37747077, 2023).
tumor (continued). "Considering the importance of NRP1 in tumor development and its relevance to RCC1 in a variety of tumors, combined with RCC1 involved in CAF and the tumor infiltration of CD8+ T cells, we believe that RCC1 might be a potential new tumor target involved in the immunosuppressive function of NRP1." (PMID 34298996, 2021). "In addition, upstream RCC1 may be regulated by Myc, and altered RCC1 influences DNA damage repair, triggering tumor progression." (PMID 34924821, 2021). "Based on our data, RCC1 may play a tumor-promoting role in CLO." (PMID 34924821, 2021). "We then used shRNA to knockdown the expression of RCC1 in PANC1 cells, and tested its effect on cell proliferation in culture and tumor formation in vivo." (PMID 41391757, 2025). "These patterns reinforce RCC1’s classification as an oncogene and USP53’s potential role as a tumor suppressor, further validating RCC1’s therapeutic relevance." (PMID 40163507, 2025). "Using unsupervised clustering analysis, we found that many OS-known genes were differentially upregulated (Rrp9, Rcc1, Ran), while others were downregulated (Mylk, Nid2) in the BMT and tumor cells compared to the control BM cells." (PMID 38182577, 2024). "The results suggest that RCC1/SNHG3/SNHG12 are involved in the immune infiltration process to some extent and play an important role in immune-tumor interactions." (PMID 36148010, 2022). "However, due to the inability of HPNE-KRAS cells to form tumor in mice, we were unable to use HPNE cells to test the functional roles of RCC1 and SIRT3 in vivo." (PMID 41391757, 2025). "In xenograft models, RCC1 knockdown in combination with 5-FU or Doxo suppressed tumor growth with no evident systemic toxicity observed." (PMID 41281944, 2025). "Obviously, RCC1 and RCC2 expressed higher protein level in tumor tissues than in normal tissues." (PMID 38434981, 2024). "It is indicated that RCC1 and RCC2 might mediate tumor progression and RCC2 may play an important role in regulation of immunotherapeutic effects on LUAD." (PMID 38434981, 2024). "Therefore, RCC1 and RCC2, serving important roles in tumor progression, have the potential to be prognostic biomarkers for LUAD." (PMID 38434981, 2024). "We found that the RCC1 knockdown significantly slowed the tumour growth than the negative control group." (PMID 33630417, 2021). "However, in the tumor tissues of KICH (p < 0.001) and PCPG (p < 0.01), the expression level of RCC1 is lower than the corresponding normal tissues." (PMID 34298996, 2021). "In THYM, the expression of RCC1 is not only negatively correlated with CAF, but also positively correlated with CD8+ T cell tumor infiltration, which may imply that targeted drugs designed for RCC1 can effectively assist immunotherapy against THYM." (PMID 34298996, 2021). "And, to explore the function of RCC1 in vivo, we established tumour models in C57BL/6J mice by transplanting RCC1‐shRNA‐Lewis cells and the negative control cells." (PMID 33630417, 2021). "In addition, it also advances the understanding of the impact of RCC1 on tumor immunology with significant correlation to CAF and tumor-infiltrating CD8+ cells." (PMID 34298996, 2021). "Genes CBX3, RCC1, TMOD3, and NOA1 (Cluster A) and TOP1, PDCD5, and THRAP3 (Cluster B) were upregulated for both datasets in PCa tissue vs. normal gland or normal adjacent to tumor tissue." (PMID 32640729, 2020). "The reason for the different effects of RCC1 on different tumor types is not yet clear, but research on its role in the cell cycle, apoptosis, and genome stability has significant prospects." (PMID 33102517, 2020). "Together, these functional studies with nondegradable Skp2AA demonstrate that knockdown of RCC1 could suppress the growth of STS tumor in vivo by downregulating the Skp2 abundance to block the cell proliferation." (PMID 38561375, 2024). "However, combined overexpression of non-degradable Skp2AA with RCC1 knockdown significantly resumed the tumor growth in shRCC1+Skp2AA group." (PMID 38561375, 2024).
tumor (continued). "Next, we confirmed whether RCC1 could influence the immune cells in tumour microenvironments or not." (PMID 33630417, 2021). "Importantly, RCC1 overexpression has been reported to accelerate both cell cycle progression and DDR in CRC cells, suggesting that its inhibition could impair these processes and sensitize tumor cells to DNA-damaging agents." (PMID 41281944, 2025). "Notably, the negative correlations of four key markers, UBE2T, TEDC2, RCC1, and FAM136A, with stromal, immune, and ESTIMATE scores suggest that the high expression of these genes in LUAD may contribute to tumor growth and malignant behaviors by inhibiting the role of stromal and immune cells." (PMID 39553728, 2024).
colorectal (1 paper, 2021). "Previous studies have found that RCC1 may play a role in the development of tumors, but little is known about the relationship between RCC1 and colorectal liver oligometastases (CLOs)." (PMID 34924821, 2021).
gastrointestinal tumors (1 paper, 2021). "Thus far, there is no literature on the prognostic role of RCC1 in gastrointestinal tumors." (PMID 34298996, 2021).
infection (1 paper, 2011). The state of being infected such as from the introduction of a foreign agent such as serum, vaccine, antigenic substance or organism. "Based on our finding that Crm1 can be retained on chromatin during influenza virus infection, we tested whether infection causes an increase in formation or stability of Crm1-Ran-Rcc1 complexes on chromatin." (PMID 21909257, 2011).
retinopathy (1 paper, 2022). "Of the RCC1 proteins, the first has no obvious orthologs in higher eukaryotes, but the second shares domain architecture with human RCBTB1, a protein mutated in a rare form of retinopathy for which an effect on Ran was postulated." (PMID 34565293, 2022).
RCC1 also shares sentences with these, for which no sentence is quoted: ovarian carcinoma (3 papers); acute myeloid leukemia (2); adenocarcinoma (2); acute kidney injury (1); B cell lymphoma (1); bacterial infection (1); biliary tract cancer (1); brain cancer (1); chronic lymphocytic leukaemia (1); clear cell carcinoma (1); colorectal adenoma (1); endometrial cancer (1); familial breast cancer (1); giant cell tumor (1); head and neck squamous cell carcinoma (1); hepatocellular carcinoma (1); kidney cancer (1); liver cancer (1); lymphoma (1); malignant peripheral nerve sheath tumor (1); mantle cell lymphoma (1); Microcystic Meningioma (1); neurofibromatosis 1 (1); non-alcoholic fatty liver disease (1); plasma cell neoplasm (1); serous ovarian carcinomas (1); squamous cell carcinoma (1); thymoma (1).